PRAME (PRAME nuclear receptor transcriptional regulator)
Diseases named in the same sentence as PRAME in open-access papers (continued):
Sharing a sentence is not in itself a finding about the gene and the disease.
melanoma (continued). "In a study published in 2018 by Lezcano C., carried out on 400 melanocytic tumors, 87 % of metastatic melanomas and 83.2 % of primary melanomas were positive for PRAME." (PMID 39862670, 2025). "PRAME (Preferentially Expressed Antigen in Melanoma) is among the more recently adopted immunohistochemical markers for cutaneous melanoma." (PMID 41155720, 2025). "PRAME overexpression is observed in 88% of primary melanoma tissues and 95% of metastatic tissues, and its marked overexpression in melanoma tumor samples has led to its recognition as an immunotherapy target for melanoma treatment." (PMID 41153267, 2025). "Approximately 50% of primary and metastatic UM tumors express PRAME, and T cells engineered with PRAME-specific TCRs have demonstrated selective cytotoxicity against PRAME-positive melanoma cell lines." (PMID 40725830, 2025). "Preferentially expressed antigen in melanoma (PRAME) is frequently expressed in numerous solid tumors and hematological malignancies." (PMID 40152485, 2025). "The antigen PReferentially expressed Antigen in MElanoma, PRAME, was shown to be a T cell target for acute myeloid leukemia after stem cell transplantation, without overt toxicity." (PMID 39858024, 2025). "In another study carried out in 2020 on 155 cases of metastatic melanoma, 97.4 % of melanomas expressed PRAME diffusely." (PMID 39862670, 2025). "Preferentially Expressed Antigen in Melanoma (PRAME) has emerged as a promising diagnostic, prognostic, and therapeutic marker in melanoma." (PMID 40868240, 2025). "Treatment with DNA methyltransferase inhibitors like decitabine has been shown to upregulate PRAME in multiple tumor cell lines, including melanoma, sarcoma, and leukemia, thus improving antigen visibility to cytotoxic T cells." (PMID 40868240, 2025). "One of these markers, PRAME (PReferentially expressed Antigen in MElanoma), raises a high degree of suspicion for melanoma when there is an increased cellular density of PRAME‐expressing cells." (PMID 40700516, 2025). "Studies have confirmed PRAME as a valuable tool; it was initially shown that diffuse PRAME expression is present in 90% of conventional melanomas and that increasing dysplasia of melanocytic nevi corresponds with greater PRAME expression." (PMID 41562714, 2025). "PRAME (PReferentially expressed Antigen in MElanoma) is a frequently positive marker to distinguish melanoma from other cancers." (PMID 39862670, 2025). "Our study supports PRAME as a useful marker in distinguishing melanomas from benign melanocytic lesions." (PMID 41153267, 2025). "UM is a highly metastatic cancer, and preferentially expressed antigen in melanoma (PRAME) was identified as an oncogene and biomarker for metastasis." (PMID 40988976, 2025). "In total, 8 of 10 (80%) SSM with prominent nests and 13 of 26 (50%) nested melanomas were found to have PRAME expression in the junctional and/or dermal compartment." (PMID 40941765, 2025). "They described a diffuse positivity for PRAME in around 90% of conventional melanomas but only in 0.7% of nevi." (PMID 40941765, 2025). "PRAME (PReferentially expressed Antigen in Melanoma) is also known as MAPE (Melanoma Antigen Preferentially Expressed in tumors), OIP4 (OPA-Interacting Protein 4), and CT130." (PMID 40961095, 2025). "The emergence of PRAME expression as a potential biomarker adds a valuable tool for differentiation, as PRAME is more frequently and intensely expressed in melanoma than in CCS." (PMID 40004764, 2025). "Our results extend these observations by showing that diffuse PRAME expression was uncommon in this group, underscoring the limited sensitivity of PRAME for the recognition of nested melanoma." (PMID 40941765, 2025). "The emerging marker Preferentially Expressed Antigen in Melanoma (PRAME) is gaining traction for its ability to distinguish melanomas from benign nevi, especially when used alongside conventional markers." (PMID 40984902, 2025).
melanoma (continued). "Modern histopathology routinely includes immunohistochemical stains, such as Sox-10 (Sry-related HMg box gene 10), Melan-A (Melanoma antigen recognised by T cells 1), and PRAME (Preferentially Expressed Antigen in Melanoma)." (PMID 41562710, 2025). "Background/Objectives: PRAME (Preferentially Expressed Antigen in Melanoma) is a promising immunohistochemical marker for distinguishing melanoma from benign melanocytic lesions, though optimal thresholds remain uncertain." (PMID 41153267, 2025). "It has been reported that several types of STS highly express CTAs, and MAGE, NY‐ESO‐1, and preferentially expressed antigen of melanoma (PRAME) are the most commonly expressed and studied CTAs in sarcomas." (PMID 40152485, 2025). "PRAME, or Preferentially-Expressed Antigen in Melanoma, is an IHC marker that is mainly used in the differential diagnosis of benign and malignant melanocytic lesions." (PMID 40507250, 2025). "In melanoma cases, PRAME expression of ≥75% was observed in 8 of 12 metastatic melanomas (66.7%), 7 of 10 SSM (70%), 4 of 5 NM (80%), 9 of 10 LM (90%), and in all cases of ALM, LMM and mucosal melanomas (100%)." (PMID 41153267, 2025). "Pathologists often use a laboratory stain called PRAME (PReferentially expressed Antigen in MElanoma) to help distinguish melanoma from benign skin lesions, but interpretation can be challenging." (PMID 41562714, 2025). "The distribution of PRAME expression among melanoma subtypes was: 100% in SSM, 80% in LMM, 91.4% in NM, and 87.8% in ALM." (PMID 41153267, 2025). "In contrast, superficial spreading melanomas with prominent nests showed PRAME positivity in 60% of cases, which is in keeping with previous reports on PRAME expression in conventional SSM." (PMID 40941765, 2025). "The PRAME antibody (PRAME-PReferentially expressed Antigen in MElanoma) is a recent and more efficient marker for differentiating nevi from melanomas, with preferential staining in melanoma in relation to benign lesions." (PMID 40614549, 2025). "A significant difference in PRAME expression was observed between the melanoma group and benign melanocytic lesions." (PMID 41153267, 2025). "This differential expression of PRAME in melanoma has introduced PRAME immunohistochemistry as a promising ancillary diagnostic tool." (PMID 40227827, 2025). "A genomic signature is derived from the extracted mRNA, specifically analyzing the expression of two genes known to increase in melanoma: PRAME (preferentially expressed antigen in melanoma) and LINC (LINC00518, long intergenic noncoding RNA 518)." (PMID 40422036, 2025). "Herein, we present the findings of PRAME expression in three cases of transdifferentiated melanomas." (PMID 39625060, 2025). "Rare, isolated case reports and a recent single study have reported strong and diffuse PRAME expression in dedifferentiated melanomas; however, its expression in transdifferentiated melanomas remains underexplored." (PMID 39625060, 2025). "PRAME expression is also a common event in melanoma and was previously investigated for treatment purposes." (PMID 40941765, 2025). "Superficial spreading melanomas and nodular and lentigo maligna melanomas also express PRAME in 88.2–90.9% of cases." (PMID 40507250, 2025). "Ongoing research into the molecular role and mechanism of action of PRAME in skin cancer continues to open new avenues in both diagnostics and therapeutics, with the potential to transform the management of melanoma and related skin cancers." (PMID 38338862, 2024). "Future research should also focus on exploring the therapeutic potential of modulating TET2 activity and its impact on PRAME expression, potentially leading to novel strategies for blocking melanoma initiation and progression." (PMID 39091741, 2024). "Taken together, these results demonstrate that restoration of 5hmC marks by ectopic TET2 expression in cultured melanoma cells suppresses PRAME gene and protein expression levels." (PMID 39091741, 2024).
melanoma (continued). "It has been demonstrated that SOX9 reduced PRAME expression, reinstating melanoma cell sensitivity to RA." (PMID 38338862, 2024). "Single-cell multiplex imaging of melanoma precursors revealed that diminished 5hmC coincides with PRAME upregulation in premalignant cells." (PMID 39091741, 2024). "PRAME was expressed in 111 lesions, including various malignancies such as melanoma, synovial sarcoma, and myxoid liposarcoma, with varying degrees of diffuse positivity." (PMID 38338862, 2024). "Preferentially Expressed Antigen in Melanoma (PRAME) was initially discovered as a melanoma antigen recognized by autologous T cells." (PMID 38030788, 2024). "Specifically, PRAME is more commonly expressed in invasive melanomas compared to benign nevi and in situ melanomas, making it a valuable tool in differentiating these stages of melanoma progression." (PMID 39451258, 2024). "The PRAME protein is commonly found in several solid tumor subtypes, ranging from melanoma to breast cancer and lung cancer." (PMID 39337333, 2024). "Among the samples, 76.5% (52/68) were positive for S-100, 94.1% (64/68) for HMB-45, 83.6% (56/67) for Melan-A, 100% (29/29) for SOX-10, and 76% (19/25) for PRAME (preferentially expressed antigen in melanoma)." (PMID 39728033, 2024). "Out of a sample of 29 mucosal melanomas, 20 (83.3%) had high PRAME expression, correlating to a worse prognosis overall." (PMID 39451258, 2024). "PRreferentially expressed Antigen in MElanoma (PRAME) is a 509-amino-acid protein found in the nuclear and cytoplasmic space of several different cell types in the human body." (PMID 39451258, 2024). "Some of the top upregulated genes included Interferon Induced Transmembrane Protein 3 (IFITM3), Preferentially Expressed Antigen in Melanoma (PRAME), and Deleted in Azoospermia-like (DAZL)." (PMID 38468866, 2024). "The preferentially expressed antigen in melanoma (PRAME), a cancer-testis antigen, is abnormally expressed in AML and does not exist in normal hematopoietic cells." (PMID 38596687, 2024). "One such marker that has garnered increasing attention in the realm of cutaneous pathology is PRAME (PReferentially expressed Antigen in MElanoma)." (PMID 39727621, 2024). "We demonstrated wide-ranging expression of PRAME mRNA and protein across melanoma subtypes, gynecologic cancers (ovarian and endometrial), lung (SCLC and NSCLC), and TNBC, consistent with previous reports." (PMID 39659431, 2024). "They found 64% of the melanomas positive for PRAME staining in >76% of the cells compared to 26% of the melanomas in our study." (PMID 39335694, 2024). "Twenty-six (26.09%) of the melanomas showed diffuse PRAME staining in over 76% of the tumor cells (4+), and 8.7% showed PRAME staining in 51 to 75% of the cells (3+), while 8% were entirely negative for PRAME." (PMID 39335694, 2024). "The overexpression of PRAME in melanomas represents a significant opportunity for cancer immunotherapy." (PMID 38338862, 2024). "PRAME was broadly expressed across tumors harboring oncogenic mutations, e.g. BRAF/NRAS-mutated melanoma or KRAS or EGFR mutant NSCLC, in accordance with a previous report." (PMID 39659431, 2024). "PRAME (PReferentially expressed Antigen in Melanoma) immunohistochemistry has proven helpful in distinguishing malignant from benign melanocytic tumors." (PMID 39335694, 2024). "In this regard, several studies have identified PRAME as a marker of primary and metastatic melanomas with high sensitivity (>90%) and specificity in the context of melanocytic lesions." (PMID 38338862, 2024). "Because PRAME is positive in almost all melanoma cells, in PRAME+ melanomas, even small microsatellites can be detected, and would otherwise be at risk of being missed on scanning H&E." (PMID 39451258, 2024). "We observed a marked reduction in 5hmC binding to the 5’ promoter region of the PRAME gene in melanomas compared to nevi." (PMID 39091741, 2024).
melanoma (continued). "Using pathophysiologic studies of clinical samples and molecular studies in cell lines, we have established a novel and potentially important function forTET2-mediated DNA hydroxymethylation in negatively regulating PRAME expression in melanoma." (PMID 39091741, 2024). "We studied PRAME IHC expression in 46 thin melanomas and 39 melanocytic nevi, mostly dysplastic nevi." (PMID 39335694, 2024). "Specifically, PRAME gene expression is significantly increased in melanomas related to SN and immunoreactivity is subsequently seen more frequently in SM." (PMID 38397186, 2024). "In other studies, lentigo maligna and lentigo maligna melanomas have similar PRAME expressions compared to superficial spreading melanomas." (PMID 39335694, 2024). "Studies have revealed that PRAME is expressed in the majority of melanomas, including both in situ and invasive types, but is rarely detected in benign nevi and melanocytic lesions." (PMID 39451258, 2024). "This study found that both primary and metastatic dedifferentiated and undifferentiated melanomas exhibited strong and diffuse nuclear PRAME staining, effectively distinguishing them from atypical fibroxanthoma and pleomorphic dermal sarcoma." (PMID 38338862, 2024). "PRAME is a dominant repressor of retinoic acid (RA) signaling in melanoma and acute myeloid leukemia (AML) by interaction with the Enhancer of Zeste Homolog 2 (EZH2) and the RA receptor α (RARα) at RA response elements (RAREs)." (PMID 39550391, 2024). "In cutaneous pathology, PRAME expression has been predominantly studied in melanocytic lesions, where its detection by IHC has proven useful in supporting the diagnosis of melanoma." (PMID 39727621, 2024). "In both melanoma and lung datasets, a proportion of PRAME+ tumors have pre-existing immune infiltrates, including T cells." (PMID 39659431, 2024). "PRAME, a cancer testis antigen, is selectively expressed in various cancers, including melanoma, and plays a key role in promoting tumorigenesis through inhibition of retinoic acid signaling, epithelial-to-mesenchymal transition, and immune evasion." (PMID 39451258, 2024). "Background/Objectives: Preferentially expressed antigen in melanoma (PRAME), a member of the cancer testis antigen family, is a promising target for cancer immunotherapy." (PMID 38541782, 2024). "PRAME, as its name implies, was first identified in melanoma cells and has been demonstrated to increase metastatic potential through repression of RAS, promotion of EMT, and promotion of an immunologically “cold” tumor microenvironment (TME)." (PMID 39451258, 2024). "In thicker melanomas, however, there was regional variation in the intensity of the nuclear expression of PRAME, equalling 4+ PRAME." (PMID 38338862, 2024). "Despite these challenges, the potential of PRAME as a therapeutic target in melanoma is significant." (PMID 38338862, 2024). "Many studies have been performed to explore the frequency of PRAME expression in melanoma compared with benign tumors." (PMID 39451258, 2024). "In melanoma, PRAME is typically highly expressed, in contrast to its weak or absent expression in benign nevi, thereby improving the accuracy of differential diagnoses." (PMID 38338862, 2024). "Preferentially expressed antigen in melanoma (PRAME) belongs to the family of cancer testis antigens." (PMID 38541782, 2024). "These traits all help to explain the poorer prognosis observed in melanomas and other malignancies with elevated PRAME expression." (PMID 39451258, 2024). "Three malignancies from different lineages (melanoma, seminoma, and synovial sarcoma), characterized by frequent yet variable PRAME expression, were studied." (PMID 38541782, 2024). "From its diagnostic potential to its role as a diagnostic and prognostic marker and as a target for innovative immunotherapies, PRAME is poised to play a pivotal role in the future of melanoma management." (PMID 38338862, 2024).
melanoma (continued). "Preferentially Expressed Antigen in Melanoma (PRAME) and Ten-Eleven Translocation (TET) dioxygenase-mediated 5-hydroxymethylcytosine (5hmC) are emerging melanoma biomarkers." (PMID 39091741, 2024). "PRAME acts through the retinoic acid receptor (RAR) signaling pathway in melanoma and other cancer cells and RA signaling is necessary for male fertility." (PMID 38424516, 2024). "PRAME is a remarkable protein with unique properties that aid in the diagnosis, prognosis, and treatment of melanoma." (PMID 39451258, 2024). "Restoring 5hmC levels via TET2 overexpression notably reduced PRAME expression in melanoma cell lines." (PMID 39091741, 2024). "Immunohistochemistry and the use of markers such as PRAME can be very helpful in distinguishing melanoma from other malignancies such as clear cell sarcoma." (PMID 38793100, 2024). "Stephen Koh’s lab found PRAME positivity in 82% of spitzoid melanomas and only 20% of benign spitz nevi." (PMID 39451258, 2024). "TET2 is significantly down-regulated in melanoma as compared to melanocytes in healthy skin, 5-hmC levels are lower, and PRAME expression is higher." (PMID 39091741, 2024). "PRAME (PReferentially expressed Antigen in MElanoma) is a cancer-testis antigen that is expressed by melanoma cells and was isolated by autologous T cells in a melanoma patient." (PMID 37796789, 2023). "Multiple studies have shown that the expression of PRAME is abnormal in different tumors, including melanoma, hematological malignancies, breast cancer, lung cancer, and sarcoma." (PMID 36980687, 2023). "PRAME (PReferentially expressed Antigen in MElanoma) is a biomarker studied in various human cancers." (PMID 37796789, 2023). "Immunohistochemical analysis for PRAME (preferentially expressed antigen in melanoma) has become increasingly used in the diagnosis of CM." (PMID 37958863, 2023). "One of the earliest CTAs for which molecular function was defined was PRAME (preferentially expressed antigen in melanoma-CT130)." (PMID 36980267, 2023). "Among the top 20 upregulated genes were the alpha fetoprotein (AFP) gene, several genes of the melanoma antigen (MAGE) protein family, and other melanoma-associated genes (MAGE-A4, -10, -12, -B-2; DSCR8, PRAME)." (PMID 37592303, 2023). "One of the targets is the cancer-testis antigen PRAME (preferentially expressed antigen in melanoma), which is currently exploited for its capacity in T cell-based immunotherapy." (PMID 37173882, 2023). "PRAME (preferentially expressed antigen in melanoma) has been identified as an antigen recognized by cytotoxic T lymphocytes, which is currently exploited for CAR-T cell therapy." (PMID 37173882, 2023). "Preferentially expressed antigen in melanoma (PRAME), a coding human leucocyte antigen (HLA)-A24, was first reported as a cancer/testis antigen in 1997." (PMID 36980687, 2023). "With insights on molecular signatures of melanomas, several immunohistochemical stains with a more diagnostic role have become available that include PReferentially expressed Antigen in Melanoma (PRAME) and p16." (PMID 38076247, 2023). "Preferentially expressed antigen in melanoma (PRAME) is a human melanoma antigen originally identified by cDNA expression cloning targeting melanoma-reactive cytotoxic T cells." (PMID 36910848, 2023). "One study assessed the immunoexpression of PRAME in 400 melanocytic tumors, including primary melanomas, metastatic melanomas, and melanocytic nevi." (PMID 37958863, 2023). "PRAME is a cancer testis antigen (CTA, Opa-interacting protein 4) expressed especially in melanomas, among other malignant neoplasms, such as sarcomas, renal cell carcinoma, non-small cell lung cancer and ovarian cancer." (PMID 37047361, 2023). "PRAME (PReferentially expressed Antigen in MElanoma) is a cancer testis antigen that is frequently expressed in melanoma compared to benign melanocytic proliferations and nevi." (PMID 37047361, 2023).